FOXO3 (forkhead box O3)
Diseases named in the same sentence as FOXO3 in open-access papers (continued):
Sharing a sentence is not in itself a finding about the gene and the disease.
leukemia (42 papers, 2010 to 2025). A malignant (clonal) hematologic disorder, involving hematopoietic stem cells and characterized by the presence of primitive or atypical myeloid or lymphoid cells in the bone marrow and the blood. "Additionally, FoxO1 and FoxO3 are frequently mutated or hyper-upregulated in leukemia, and pharmacological inhibition of FoxO1 dramatically reduces the aberrant growth of leukemia, indicating the fundamental roles of FoxO1 and FoxO3 in blood cancer." (PMID 37594999, 2023). "Similarly, FOXO3 is associated with the apoptotic effect of imatinib in leukemia cells via Bim induction." (PMID 29299162, 2017). "In contrast, we have shown that FOXO3 plays a pivotal role in leukemia stem cells and progression of leukemia." (PMID 37773170, 2023). "We relate this FOXO3-specific leukaemia-protective role to suppression of glycolysis based on integrated analysis of CRISPR-data and gene sets induced or suppressed by FOXO1 and FOXO3." (PMID 36670235, 2023). "On the other hand, FOXO3 acts as a tumor suppressor, and phosphorylation of FOXO3 by FLT3-ITD results in inactivation of FOXO3-mediated apoptosis in leukemia with FLT3-ITD mutation." (PMID 38007419, 2023). "In CML, FOXO3 plays an essential role for long-term maintenance of leukemia-initiating stem cells that are resistant to tyrosine kinase inhibitor (TKI) therapy, preventing complete molecular response, and causing recurrence of CML." (PMID 31591479, 2020). "The transcriptional activity of FoxO3 is inhibited by the phosphorylation of this factor via the PI3K-Akt pathway in leukemia cells." (PMID 25536335, 2014). "This suggests that if p16INK4A is deleted during leukemia development, FOXO3 levels elevate and FOXO3 has to be inactivated by deregulation of the PI3K-PKB pathway to prevent FOXO3-induced cell death." (PMID 23828551, 2013). "Our results demonstrate for the first time a link between loss of p16INK4A and FOXO3-inactivation / hyperactive PKB-signaling in T-ALL and both cancer-associated alterations correlate with therapy resistance in leukemia cells." (PMID 23828551, 2013). "The-reconstitution of the cell cycle inhibitor p16INK4A, which sensitizes ALL cells to mitochondria-induced cell death, represses FOXO3 protein levels and reduces the dependency of these leukemia cells on PI3K-PKB signaling." (PMID 23828551, 2013). "This study aligns with findings that FOXO3 activity is important for maintenance of leukaemia-initiating cells in myeloid leukemias, and highlights that individual FOXOs may perform specific functions in a lineage-dependent manner." (PMID 37275916, 2023). "miR-708-5p targeting of FOXO3 may also help to prevent resistance and relapse by stopping leukemia-initiating cell self-renewal." (PMID 29050362, 2017). "In leukemia, miR-9 targets FoxOs (FoxO1 and FoxO3) to promote cell differentiation." (PMID 26593208, 2015). "One explanation for PKB hyperactivation might be that T-ALL cells frequently carry a heterozygous deletion of the PTEN gene locus, which leads to increased PI3K-PKB signaling and thereby inactivation of the PKB target FOXO3 in leukemia cells." (PMID 23828551, 2013). "This indicates that FOXO3 induces caspase-dependent cell death in T-ALL leukemia cells." (PMID 23828551, 2013). "As both FOXO3 and FOXO1 inhibited leukaemia growth in our assays, we treated 697 and REH cells with Selinexor to increase pan-FOXO activity, achieving IC50 in the 50–100 nanomolar range." (PMID 36670235, 2023). "Consistent with our finding, several lines of evidence have recently highlighted the roles of FOXN3, FOXO3, FOXO4, and FOXP3 in leukemia." (PMID 36292640, 2022).
leukemia (continued). "FOXO3 can also act as an oncogene by increasing PI3K activity to promote resistance and by maintaining leukemia-initiating cell (LIC) populations." (PMID 29050362, 2017). "Using Affymetrix gene expression profiling we identified DEPP as a FOXO3-regulated gene in neuroblastoma as well as CEM-C7H2 leukemia cells and found DEPP also induced by FOXO3 at the protein level." (PMID 25261981, 2014). "Deletions of 6q involving FOXO3 and/or PRDM1 may therefore promote leukaemia survival partly by reducing sensitivity to leptin receptor signalling." (PMID 36670235, 2023).
melanoma (42 papers, 2009 to 2025). A malignant, usually aggressive tumor composed of atypical, neoplastic melanocytes. "Phospho(Ser473)-AKT1 has been linked to nuclear translocation and activation of FOXO3 in melanocytes and melanoma." (PMID 40562100, 2025). "Aberrant expression of miR-182 promotes melanoma metastasis by inhibiting microphthalmia-associated transcription factor and FOXO3." (PMID 31007608, 2019). "miR-182, a member of a miRNA cluster in chromosomal locus 7q31–34, is frequently described as amplified in A375 melanoma cell lines, acting as an oncomiR through the suppression of transcription factors forkhead box O3 (FOXO3) and microphthalmia-associated transcription factor (MITF)." (PMID 33348804, 2020). "In melanoma, overexpression of miR-182 promotes survival, migration, and metastasis by directly repressing the tumor suppressors FOXO3 and microphthalmia-associated transcription factor-M; and expression of miR-182 increases with progression from primary to metastatic melanoma." (PMID 24627810, 2014). "Thus, in melanoma cells, miR-182 modulate the expression of both FOXO3 and microphthalmia-associated transcription factor (MITF)." (PMID 32309538, 2013). "Aberrant miR-182 expression promotes melanoma metastasis by repressing FOXO3 and microphthalmia-associated transcription factor, which indicates that miR-182 may promote the metastasis of HCC through targeting on some genes." (PMID 22681717, 2012). "Relatively less is known about the downstream genes that are regulated by MITF and FOXO3, which are evidently important for melanoma progression and metastasis." (PMID 21072171, 2010). "In melanoma, miR‐182 upregulation induces metastasis by targeting Forkhead Box O3 (FOXO3)." (PMID 39617640, 2024). "In melanoma, dysregulation of miR-182 promotes tumor metastasis expressed by targeting FoxO3." (PMID 37127752, 2023). "Overexpression of miR-182 stimulates melanoma cell migration and invasion through the direct downregulation of MITF and FOXO3 expression; studies on melanoma cell lines and tissue samples have found that its expression increases gradually from primary to metastatic stage." (PMID 33203119, 2020). "In addition, we showed that suppressed expression of NOVA1 enhanced forkhead box O3a (FOXO3a) expression while inhibited AKT expression in melanoma cell." (PMID 29498217, 2018). "MiR-182-5p has been reported to promote melanoma metastasis by repressing FOXO3." (PMID 29361949, 2018). "In addition, Jaspine B inhibited melanoma cell growth by inhibiting the phosphorylation of Forkhead box O3 (FOXO3) and by inducing apoptosis." (PMID 28862650, 2017). "The depletion of miR-182 reduces invasiveness and induces melanoma cell death by suppressing the expression of transcription factors FOXO3 and MITF, suggesting that its increased expression may be associated with certain aspects of melanoma biology." (PMID 21072171, 2010). "FOXO3 may well induce apoptosis in melanoma cells by the expression of requisite genes." (PMID 34290746, 2021).
Obesity (35 papers, 2012 to 2025). Accumulation of substantial excess body fat. "Together, these findings establish the significance of the loss of FOXO3 in macrophages in colonic pathobiologies and provide conceptual advances in our understanding of how obesity, via both its mediators and metabolites, promotes these disease processes." (PMID 35323693, 2022). "Obesity mediators and metabolites cause a loss of FOXO3 in colonic cells, revealing an important role of FOXO3 in obesity-mediated changes in the colon." (PMID 35323693, 2022). "Here, we demonstrated that the loss of FOXO3 in macrophages plays a critical role in obesity-mediated inflammation and tumorigenesis in the colon." (PMID 35323693, 2022). "Obesity, characterized by augmented inflammation and tumorigenesis, is linked to genetic predispositions, such as FOXO3 polymorphisms." (PMID 35323693, 2022). "In the human population, obesity is accompanied by genetic predispositions such as polymorphisms of the FOXO3 gene that lead to its lowered levels." (PMID 35323693, 2022). "A2AR ligation additionally enhances in vivo activation of FoxO1 and FoxO3 with evidence of enhanced autophagic flux upon injection of the liposome-associated A2AR agonist in a mouse obesity-induced OA model." (PMID 33441836, 2021). "We have previously demonstrated that obesity-mediated by high-fat diet and deficiency in FOXO3 leads to LDs accumulation and activates MYC in mouse colon." (PMID 34845203, 2021). "Studies have found that human obesity is associated with polymorphisms of the FOXO3 gene." (PMID 40002988, 2025). "In human populations, obesity is associated with polymorphisms in the FOXO3 gene." (PMID 35323693, 2022). "In humans, obesity is associated with polymorphisms in the FOXO3 gene." (PMID 35323693, 2022). "Therefore, as HFD obesity causes increased macrophages as well as loss of FOXO3 in mouse colon, we determined that the loss of FOXO3 in macrophages contributes to obesity-mediated colonic pathobiology." (PMID 35323693, 2022). "Consequently, macrophage metabolism is often abnormal in disease states, and their loss of FOXO3-mediated metabolic reprogramming presents a potential therapeutic target for colonic inflammation and tumorigenesis facilitated by obesity." (PMID 35323693, 2022). "Therefore, elucidating how obesity, through loss of FOXO3 in macrophages, promotes colonic inflammation and tumorigenesis will provide conceptual advances in understanding this worldwide epidemic and the mechanisms driving these human pathobiologies." (PMID 35323693, 2022). "Exceptionally, fat mass- and obesity-associated (FTO) genes have been shown to be associated with obesity and TL, and the FOXO3 G allele of SNP rs2802292 significantly protected against aged-related TL loss relative to that of carriers of the common TT genotype." (PMID 33507936, 2021). "Additionally, obesity mediators and metabolites cause a loss of FOXO3 in colonic cells." (PMID 35323693, 2022). "Therefore, it is plausible that the loss of FOXO3 in both colonic cells and macrophages may be critical in driving obesity-mediated colonic inflammation and tumorigenesis." (PMID 35323693, 2022). "Therefore, we hypothesized that the loss of FOXO3 via obesity contributes to the development of pathobiologies in various tissues, especially the colon." (PMID 35323693, 2022). "However, except for a slight difference between rs2802292*G and HbA1c in both middle-aged cohorts, no other relationship was observed among the lipid profiles, the risk for T2DM, obesity and other cardiovascular diseases in all three cohorts for any FOXO3 variant and haplotype." (PMID 25993007, 2015). "This study explored how variations in key genes related to obesity—FOXO3A (forkhead box O3), AMPK (protein kinase AMP-activated), and POMC (proopiomelanocortin)—are associated with extreme obesity (EOB)." (PMID 39484290, 2024).
Obesity (continued). "Our study showed that obesity mediators and metabolites lead to diminished levels of FOXO3 and increased macrophages in the colon, suggesting a central role of FOXO3 in metabolic reprogramming of both macrophages and intestinal epithelial cells." (PMID 35323693, 2022). "We found that in mouse colon, high-fat-diet-(HFD)-related obesity led to diminished FOXO3 levels and increased macrophages." (PMID 35323693, 2022). "Further findings would expand our understanding of mechanisms involved in obesity-related disorders mediated by the macrophage-FOXO3 axis, help us identify key regulators of other metabolic disorders and develop individualized treatment options." (PMID 35323693, 2022). "As obesity is associated with aberrant macrophages infiltrating different tissues, including the colon, we aimed to identify FOXO3-dependent transcriptomic changes in macrophages that drive obesity-mediated colonic inflammation and tumorigenesis." (PMID 35323693, 2022). "We further demonstrate that AMPK/PGC-1α-suppressed FOXO3/atrophy-specific gene transcription signaling plays an important role in fish oil-prevented obesity-induced muscle wasting." (PMID 31242648, 2019). "Data presented here demonstrate that Foxo1 and Foxo3 in CD4+ T cells likely act as a metabolic regulator that can suppress beiging with the potential capacity to accelerate obesity-induced insulin resistance." (PMID 31756626, 2019). "In a mouse model combining ischemia-reperfusion (I/R) injury and high-fat diet (HFD)-induced obesity, we identify apelin as a novel regulator of FoxO3 trafficking in cardiomyocytes." (PMID 26542760, 2015). "Together, these data revealed that systemic transcriptional changes, mediated by the loss of FOXO3 in macrophages, are similar to those seen in the colon of HFD obese mice, which suggests a critical role of the macrophage-FOXO3 axis in driving obesity-mediated colonic changes." (PMID 35323693, 2022). "Here we showed that obesity, whether directly or indirectly, drives colonic inflammation and tumorigenesis through the inactivation of FOXO3 in macrophages." (PMID 35323693, 2022). "Another study conducted in rats found that obesity accelerates ovarian follicle development and follicle loss in rats, while caloric restriction prolonged ovary lifespan by SIRT1/FOXO3a/NRF1-SIRT6 pathway, indicating the target of FOXO3 in follicle development." (PMID 34646156, 2021). "In addition, using in vitro and in vivo approaches, we identify apelin as a novel regulator of FoxO3 nucleocytosolic trafficking in cardiomyocytes in conditions combining myocardial injury and obesity." (PMID 26542760, 2015). "Taken together, these results unravel a novel function of apelin in the regulation of FoxO3 nucleocytoplasmic trafficking and may provide new insights into the mechanistic basis of obesity paradox." (PMID 26542760, 2015). "Our further study determined that the benefits of miR-122-5p inhibitor in obese mice could be abolished by silencing FOXO3, including decreasing lipid accumulation, which also demonstrated that miR-122-5p targeting on FOXO3 played a crucial role in obesity-induced mouse fatty liver diseases." (PMID 35222075, 2022). "Thus, it is plausible that the FOXO3 and LDs regulatory network, facilitated by obesity, may involve ATGL and MYC." (PMID 34845203, 2021). "Therefore, miR-122-5p/FOXO3 might be a potential therapeutic agent against obesity-related NAFLD." (PMID 35222075, 2022). "An increase of SIRT3 levels can preserve heart function and heart capillary density during obesity, and activation of the SIRT3/FOXO3 pathway can protect the heart from HFD-induced oxidative stress." (PMID 33806509, 2021). "In addition, FOXO3 and TBC1D1 have been shown to be involved in lipid accumulation, fatty acid oxidation and obesity development." (PMID 36397714, 2023).
Obesity (continued). "GSEA and KEGG analysis of obesity showed an enhancement of cytokine and chemokine pathways, whereas the results of COPD showed an upregulation of repair-related genes such as cell junctions, HIF1α, and FOXO3." (PMID 37886639, 2023). "Therefore, both Foxo1 and Foxo3 in CD4+ T cells should be molecular targets for the prevention and treatment of obesity." (PMID 31756626, 2019). "Moreover, STAT3, MCL1, PMAIP1, SOD2, FOXO3, FOS, FKBP5 may play an essential role in the genesis and growth of obesity and might serve as a possible therapeutic target." (PMID 34712134, 2021).
breast tumor (32 papers, 2008 to 2024). "Analysis of the global gene methylation profiles of a cohort of 33 familial breast tumours revealed that FOXO3 promoter methylation is significantly associated with BRCA1 mutation." (PMID 27043660, 2016). "Notably, FOXO1 and FOXO3 proteins have been implicated in the promotion of breast tumor cell invasion." (PMID 32332845, 2020). "High FOXO3 protein expression could be a biomarker of deficient DDR in breast tumors." (PMID 32332845, 2020). "Contrariwise, FOXO3 oppositely impacted the invasive capabilities of breast tumors, depending on the estrogen receptor α (ERα) status." (PMID 34771514, 2021). "Surprisingly, we also demonstrated negative correlations between FOXO3 protein expression and the expression of numerous proteins involved in various DNA repair mechanisms, suggesting that high FOXO3 protein expression in breast tumors impairs DDR." (PMID 32332845, 2020). "In particular, we found that patients with breast tumors expressing high levels of FOXO3 protein had better survival rates than patients with breast tumors expressing lower levels of this protein." (PMID 32332845, 2020). "Patients with breast tumors expressing high levels of FOXO3 protein had better MFS than patients with breast tumors expressing lower levels of FOXO3 protein (p = 4.1.10−2), which is consistent with a tumor suppressor role." (PMID 32332845, 2020). "The weak PI3K/AKT/mTOR pathway activity found in the breast tumors expressing low level of FOXO3 protein would be therefore due to a low level of various components of this pathway but not to a high level of PTEN." (PMID 32332845, 2020). "The RPPA method demonstrated a wide range of FOXO1 protein expression (ranging from 0.07 to 1.91) and FOXO3 protein expression (ranging from 0.19 to 3.98) in breast tumors." (PMID 32332845, 2020). "To better define the role of FOXO1 and FOXO3 transcriptional factors in breast carcinogenesis, we performed a comparative study of their expression at both the RNA and protein levels in a series of human breast tumors." (PMID 32332845, 2020). "We detected at least 8 samples with negative or low levels of phospho-FOXO3 (pSer-253) expression among 12 breast tumor samples expressing high levels of FOXO3, suggesting that this FOXO3 protein may be functional in a majority of these tumors." (PMID 32332845, 2020). "Low expression of FOXO1 or FOXO3 protein in breast tumors is correlated with poor clinical outcome." (PMID 32332845, 2020). "High expression of FOXO3 protein could therefore be an attractive predictive biomarker of favourable response to treatment with PARP inhibitors in breast tumors." (PMID 32332845, 2020). "To investigate the role of FOXO1 and FOXO3 genes in breast carcinogenesis, we therefore used the RPPA method to perform a comparative study of the protein expression of these two FOXO genes in a series of 218 breast tumors." (PMID 32332845, 2020). "Therefore, our results suggest that high activity of the PI3K/AKT/mTOR pathway in breast tumors would induce degradation of FOXO3 protein, but not FOXO1 protein." (PMID 32332845, 2020).